SFT2D2 (SFT2 domain containing 2)
Description:
May be involved in fusion of retrograde transport vesicles derived from an endocytic compartment with the Golgi complex.
Synonyms: UNQ512; dJ747L4.C1.2
Tractability: Antibody: UniProt predicts a signal peptide or a membrane-spanning region. PROTAC: ubiquitination databases record sites on it; its protein half-life has been measured.
Gene: Protein-coding gene on chromosome 1 (168,225,938 to 168,253,021, forward strand). Ensembl gene ENSG00000213064.
Subcellular location: Membrane
Gene Ontology:
Molecular function: protein binding
Biological process: vesicle-mediated transport
Cellular component: extracellular exosome; cytoplasm; endomembrane system; membrane
Genetic constraint (gnomAD): Loss-of-function variants: 20 observed, 25.1 expected, observed/expected ratio (o/e) 0.8, 90% interval 0.56 to 1.16. The upper end of that interval is the gene's LOEUF score, 1.16, which puts it in group 5 of 6, group 1 being the genes least tolerant of losing a copy. Missense variants: 170 observed, 185.18 expected, observed/expected ratio (o/e) 0.92, 90% interval 0.81 to 1.04. Synonymous variants: 69 observed, 69.56 expected, observed/expected ratio (o/e) 0.99, 90% interval 0.82 to 1.21.
Homologues: Orthologues: chimpanzee SFT2D2 (99% identical), rabbit SFT2D2 (95% identical), guinea pig SFT2D2 (94% identical), mouse Sft2d2 (91% identical), macaque SFT2D2 (89% identical), pig SFT2D2 (88% identical), rat Sft2d2 (88% identical), tropical clawed frog sft2d2 (74% identical), zebrafish sft2d2b (65% identical), Drosophila melanogaster CG5104 (59% identical), zebrafish sft2d2a (54% identical), Caenorhabditis elegans F27D4.7 (35% identical). Paralogues in human: SFT2D1 (64% identical), SFT2D3 (23% identical).
Diseases named in the same sentence as SFT2D2 in open-access papers:
SFT2D2 is named in the same sentence as 8 diseases in open-access papers, as found by Europe PMC text mining. Sharing a sentence is not in itself a finding about the gene and the disease. The quoted sentences say what the papers report.
breast carcinoma (3 papers, 2019 to 2026). "Among the DNA methylation features, probes such as cg03441279 in BCL9 and cg12427162 in SFT2D2 have been associated with breast cancer prognosis." (PMID 40093058, 2025). "As the next predicted gene associated with breast cancer subtyping, SFT2D2 contributes to the fusion of retrograde transport vesicles." (PMID 31480430, 2019). "Although only a few descriptive studies have been published about this gene, breast cancer SFT2D2 has been confirmed to contribute to metastatic pathogenic behaviors." (PMID 31480430, 2019).
prostate carcinoma (1 paper, 2024). A carcinoma that arises from epithelial cells of the prostate gland. "Considering that the UTR region of SFT2D2‐TBX19 shares a substantial portion of its nucleotide sequence with the parental gene SFT2D2, we investigated the potential role of SFT2D2 lncRNA in prostate cancer progression." (PMID 39540264, 2024). "Our experiments revealed that the overexpression of SFT2D2 lncRNA did not impact the proliferation, migration and invasion of prostate cancer cells." (PMID 39540264, 2024).
schizophrenia (1 paper, 2022). A major psychotic disorder characterized by abnormalities in the perception or expression of reality. "Following this theory, our study identified a potential causal gene for the risk of schizophrenia, SFT2D2, and its peripheral autoantibody levels were significantly increased in patients with schizophrenia." (PMID 36619926, 2022). "A rare variant (rs532193193) in the SFT2D2 locus was identified to be strongly associated with schizophrenia." (PMID 36619926, 2022). "It will be useful to repeat these assays in follow-up cohorts, as well as in other psychiatric diseases, to determine whether abnormalities of SFT2D2-associated humoral immunity are limited to schizophrenia and show a state-dependent feature." (PMID 36619926, 2022). "Our findings indicate that SFT2D2 is a novel gene for risk of schizophrenia, while endogenous anti-SFT2D2 IgG may underlie the pathophysiology of the immunological aspects of schizophrenia." (PMID 36619926, 2022). "Interestingly, the 2-Mb regional sequencing revealed that rs532193193 present in intron 6 of SFT2D2 (NM_199344.2) was strongly associated with schizophrenia in both the samples that carried the rs10489202T–rs11586522A haplotype and those that did not carry the rs10489202T–rs11586522A haplotype." (PMID 36619926, 2022). "The expression level of SFT2D2 mRNA increased in postmortem brain samples of patients with schizophrenia, including the pre-frontal cortex, hippocampus, and striatum (18 patients vs. 15 controls)." (PMID 36619926, 2022). "We have observed an increase in SFT2D2 mRNA expression levels in postmortem brain samples of patients with schizophrenia." (PMID 36619926, 2022). "On the one hand, circulating anti-SFT2D2 IgG can cross the blood–brain barrier to the brain and lead to targeting of SFT2D2 protein which expresses in the central nervous system, thus contributing to the illness and possibly to schizophrenia pathophysiology." (PMID 36619926, 2022). "Taken together, we hypothesized that overactive SFT2D2 in the brain and pDCs may disrupt self-surveillant homeostasis and trigger autoimmune inflammatory responses in schizophrenia." (PMID 36619926, 2022). "On the other hand, overactive SFT2D2 in the brain and pDCs may disrupt self-surveillant homeostasis and trigger autoimmune inflammatory responses in schizophrenia." (PMID 36619926, 2022). "Now, the anti-SFT2D2 IgG we found in patients with schizophrenia may have a similar mechanism." (PMID 36619926, 2022). "Third, serological assays against anti-SFT2D2 IgG were only performed in patients with schizophrenia in the acute phase and lacked the trend of changes in antibodies after anti-psychiatric medications." (PMID 36619926, 2022).
viral infection (1 paper, 2022). "SFT2D2 has also been found to be linked to IFN-I signaling that is needed nearly for all innate immune activities in the brain following a non-cytopathic viral infection." (PMID 36619926, 2022).
infection (1 paper, 2013). The state of being infected such as from the introduction of a foreign agent such as serum, vaccine, antigenic substance or organism. "Further analyses at day 140 post-infection uncovered only 3 additional upregulated genes (SCRG1, LY86, SFT2D2) in IFNR−/− mice." (PMID 23737750, 2013).
neurodegenerative disease (1 paper, 2022). A disorder of the central nervous system characterized by gradual and progressive loss of neural tissue and neurologic function. "A recent study has suggested that SFT2D2 requires for endosome-to-Golgi retrieval that may be linked to neurodegenerative diseases." (PMID 36619926, 2022).
SFT2D2 also shares sentences with these, for which no sentence is quoted: breast tumor (1 paper); psychiatric diseases (1).